IFNG (interferon gamma)
Diseases named in the same sentence as IFNG in open-access papers (continued):
Sharing a sentence is not in itself a finding about the gene and the disease.
Granuloma (226 papers, 2005 to 2026). A compact, organized collection of mature mononuclear phagocytes, which may be but is not necessarily accompanied by accessory features such as necrosis. "The past years have seen the emergence of Th1 mediators such as CXCR3/CXCR3 ligands (interferon gamma regulated CXC chemokines) as factors leading to granuloma formation, the pathogenetic hallmark of sarcoidosis." (PMID 23181555, 2012). "Similar to TNFα, IFNγ enhances the anti-mycobacterial ability of macrophages and plays an important role in granuloma development." (PMID 39918314, 2025). "Single-cell analyses of granulomas in skin sarcoidosis have revealed that IFNG is upregulated in helper T cells, including Th17.1 cells, but not in macrophages." (PMID 41463010, 2025). "BCG granulomas in mouse liver showed that relatively few T cells secrete IFNγ in a spatially polarized fashion, most likely resulting in a concentrated localized delivery to few antigen-presenting cells." (PMID 39918314, 2025). "Previous studies have demonstrated that CD137 stimulation induces the production of IFNγ by CD8+ T cells, and chronic signaling activation of CD137 has been linked to the development of granuloma." (PMID 38254759, 2024). "Compared to “healthy” lung parenchyma, the concentration of proinflammatory cytokines IL-6, IL-11, IL-17, and IFNγ, which are responsible for granuloma organization and infection focus delineation, was increased in the tuberculoma wall." (PMID 39519346, 2024). "In the acute stages of granuloma development, they exhibit a highly polarized expression of T helper Type 1 (Th1) cytokines, including interferon-gamma (IFN-γ) and tumor necrosis factor-alpha (TNF-α), along with evidence of Th17 cell signaling." (PMID 38202021, 2023). "The allergic inflammatory disease is of helper T-cell (Th1) origin, and the formation of small areas of inflammation (granulomas) is dependent on the Th1 cytokine, interferon-gamma (IFN-γ)." (PMID 36164329, 2022). "The frequency of CD4+ and CD8+ T cells that were producing the cytokines TNF-α- and IFNγ from lung granulomas, thoracic LNs, and lung tissue homogenates were measured as part of our previous study for the SIV+ group as a whole." (PMID 35467372, 2022). "Upon antigen presentation to T cells, CD4+ T cells produce interferon gamma (IFN-γ), which is involved in the enhancement of macrophage killing and plays an important role in granuloma formation." (PMID 33952660, 2021). "With MMP12 upregulation (C57/Bl6), persistent PPARγ decrease and IFNγ increase results in granuloma persistence." (PMID 33072094, 2020). "Consistently, hypercalcemia related to IRIS is known to be caused by overproduction of 1, 25-dihdroxyvitamin D3 (1, 25[OH2]D3) secreted from disease-activated macrophages together with Th1 cytokines, e.g., interferon-gamma (IFN-γ) and granuloma formation." (PMID 31905985, 2019). "This patient developed granuloma in visceral organs after cessation of IFNγ and healed after re-administration of the drug." (PMID 29996795, 2018). "Of note, LNs with granulomas that are sterile had significantly higher frequencies of CD3+ T cells producing IFNγ; CD8+ cytotoxic T cells producing IFNγ, IL-2 or TNF and CD20+ B cells producing IL-2 than CFU+ LNs." (PMID 30383808, 2018). "By contrast, T-bet deletion significantly increased proliferation of FCMs isolated from subcutaneous granulomas, consistent with previous results showing that the Th1-cell derived cytokine, IFNγ, can inhibit macrophage proliferation." (PMID 26886778, 2016). "In macaques, Tregs and IFNγ-producing effector T-cells expanded early after pulmonary TB infection, yet in vivo depletion of both IFNγ-producing and Tregs led to decreased resistance against granuloma progression." (PMID 26029205, 2015). "It is thus likely that IL-12 (through promoting IFNγ) is of similar importance in sarcoidosis granuloma formation." (PMID 25386143, 2014).
Granuloma (continued). "Following the initial proinflammatory cytokine release, CD4+ TH cells enter the lesion and release TH1-type cytokines, IL-2 and IFNγ, which facilitates the establishment of delayed-type hypersensitivity response and early granuloma formation." (PMID 23429492, 2013). "If more than a half of leukocyte infiltrate macrophages of the mouse 6S/2 were producing IFNγ, then there were less such cells detected in Gran/1 granulomas, but the amount of macrophages producing IFNγ significantly increased in Gran/2 granulomas." (PMID 24198843, 2013). "Inverse dynamics of producing IFNγ was studied in granuloma lymphocytes: almost all of the lymphocytes of Gran/1 granulomas contained IFNγ in cytoplasm; however, there were very few lymphocytes producing IFNγ detected in Gran/2 granulomas." (PMID 24198843, 2013). "A second mechanism in sarcoidosis is that granulomas are characterized by local proinflammatory activated CD4 + T lymphocytes with Th1 profile (IFNγ, IL2) stimulating TNFα production by macrophages." (PMID 24373564, 2013). "IFNγ, released by T lymphocytes, is considered to activate macrophages and dendritic cells in human and animal granulomas for struggling with tuberculous infection." (PMID 24198843, 2013). "Mice with genetic deficiencies of the TH1-specific transcription factor T-bet or IFNγ displayed enlarged schistosome granulomas and elevated IL-17 levels." (PMID 23429492, 2013). "The amount of lymphocytes synthesizing IFNγ in infiltrates of the mouse 6S/2 and Gran/2 granulomas was 20% on average, while 80% of lymphocytes in Gran/1 granulomas were stained for IFNγ (***P < 0.001)." (PMID 24198843, 2013). "Interferon gamma [IFN-γ] plays a critical role in the formation of granuloma in HP, while TLR9 appears also required." (PMID 23374544, 2013). "Granulomas in early sarcoidosis express a strong TH-1 phenotype with production of interleukin-2 and IFNγ, which results in a positive feedback loop to recruit additional TH-1 cells and IFNγ production." (PMID 22937766, 2012). "Previous studies have demonstrated that IFNγ is necessary for the development of granulomas in HP and the results from these studies demonstrate that the transcription factor T-bet plays a critical role in controlling the severity of HP." (PMID 21699708, 2011). "The S. rectivirgula exposed IL-6-/- mice had similar levels of alveolitis and granuloma formation as well as an increase in IFNγ+ T cells compared to the WT mice." (PMID 21699708, 2011). "Here, we tested the ability of granuloma-resident APCs from three- and ten-week granulomas to induce IFNγ production from newly recruited mycobacterium-specific T cells that migrated to pre-existing granulomas." (PMID 20625513, 2010). "CD11c+ cells purified from three-week granulomas were more efficient at inducing IFNγ and IL-2 production from OT-II CD4+ T-cells than CD11c+ cells from ten-week granulomas." (PMID 20625513, 2010). "Here we report that a DC-like population, characterized by CD11c+ expression, are present in acute and chronic BCG-induced granulomas, but their location, phenotype, and ability to induce IFNγ responses distinctly changes throughout the course of infection." (PMID 20625513, 2010). "Six days after adoptive transfer, cells from three- and ten-week granulomas were isolated for ex vivo recall of IFNγ production." (PMID 20625513, 2010). "In fact, the IFNγ-producing T cell population in ten-week granulomas fell below our detection level in many samples." (PMID 20625513, 2010). "CD4+ T cells from ten-week granulomas showed a dramatic decrease in both IFNγ production and LFA-1 expression compared to three-week granulomas." (PMID 20625513, 2010). "SRA expression is increased after interferon-gamma (IFN-γ) treatment or exposure to M. tuberculosis, and is highly expressed on macrophages associated with M. bovis Bacille Calmette-Guérin (BCG)-induced granulomas." (PMID 19521507, 2009).
Granuloma (continued). "Granuloma formation in sarcoidosis is mediated by increased secretion of interferon-gamma, interleukin-2, and tumor necrosis factor-alpha." (PMID 18226232, 2008). "In the human granulomas the abundance of unstimulated T cells with a high level of IFNG expression and recent TCR stimulation score indicates that a substantial fraction of cells may have been actively recognizing antigen in situ at the time of resection." (PMID 41438074, 2025). "Our study suggests that the upregulation of IFNG in the PBMCs may closely reflect the activities of systemic granuloma formation and contribute to EPL during sarcoidosis." (PMID 41463010, 2025). "CD4+IFNγ+ T cells are critical in the formation of granulomas with early containment of Mtb." (PMID 39717773, 2024). "Among the top five ranked cell types, myeloid cells, particularly MHCI+ M1 or MHCII+ M2, were commonly and heavily accumulated across all tissue clusters (i.e., MHCI+ M1 or MHCII+ M2), while IFNγ+CD8+ T cells were the most abundant adaptive cell type found in tuberculoma (5.1% of granuloma cells)." (PMID 38254759, 2024). "Since granuloma in mycobacterial infection is a type-1 granuloma that is promoted by IFNγ and inhibited by IL-10, the higher IL-10 production by iCD8− DC may be the basis for the significantly reduced granuloma formation in its recipients." (PMID 20174628, 2010). "The ability of CD11c+ cells to shield mycobacteria from local IFNγ T cell responses may be one explanation for the ability of mycobacteria to survive indefinitely in granulomas." (PMID 20625513, 2010). "Thus, assuming that the modeling conditions accurately depict the mechanisms regulating granuloma formation in the setting of sarcoidosis, careful titration of combination therapy with anti-IL-2 and anti-IFNγ is predicted to effectively attenuate disease activity." (PMID 21637752, 2011). "Gideon and collaborators also showed pro- (IFNγ) and anti-inflammatory (IL10) cytokine expression by different neutrophil subsets in granulomas from Mtb-infected cynomolgus macaques, suggesting an immunoregulatory function of neutrophils in TB granulomas." (PMID 34887853, 2021). "Granulomas were histologically similar to those observed in sarcoidosis with the recruitment of macrophages, CD4+ T lymphocytes with Th1 cytokine (IL-2 and IFNγ) production, and rare B lymphocytes." (PMID 32751786, 2020). "Granuloma formation in the liver in response to Leishmania requires the recruitment of CD4+ T cells and the release of IL-12, IFNγ and TNF, among other cytokines." (PMID 26684322, 2015). "Bronchoalveolar lavage (BAL) cells, BAL fluids, and lung tissues were obtained 60 days post-instillation for analysis of granuloma histology and pro-inflammatory cytokines (osteopontin, CCL2, and interferon gamma [IFN-γ] mRNA and protein expression." (PMID 23343389, 2013). "The induction of IFNγ and IL-12 and the depletion of IL-4 producing NK cells has been attributed to TDM as well as a role, along with IL-6 and TNFα, in stable granuloma formation." (PMID 22738036, 2012). "Since many current therapeutic efforts are aimed at generating an increase in Mtb-specific IFNγ-producing Th1 cells, we next tested the ability of DCs to re-boost newly recruited CD4+ T cells in acute and chronic granulomas." (PMID 20625513, 2010). "The present study has shown the upregulation of IFNG and IFNLR1, included in the “interferon-mediated signaling pathway,” in patients with sarcoidosis with EPL manifestation, suggesting their potential role in granuloma progression to multiple organs." (PMID 41463010, 2025). "The CD4+ T cell response plays a critical role in protective immunity against M. tuberculosis infection and is characterized by Th1 cells that secrete interferon gamma (IFN-γ) and other cytokines to activate macrophages that have phagocytosed the pathogen and promote the formation of granulomas." (PMID 35196822, 2022).
Granuloma (continued). "Whereas in the absence of MMP12 (Mmp12 KO), PPARγ increases and IFNγ decreases, resulting in granuloma resolution." (PMID 33072094, 2020). "Increase IFNγ & TNF-α levels and PMN cells & functions.Increase T helper CD4 T cells & CD8 T cells activity.Improve Ag- specific antibody response.Restored DTH response and Granuloma formation.Reduced IL-6 cytokine and bacterial load." (PMID 30534129, 2018). "Indeed, in immunocompetent subjects, clearance of internalized Cryptococcus is thought to depend on T helper 1 mediated response which results in formation of a granuloma and production of TNF-α and Interferon gamma (IFNγ)." (PMID 26688618, 2015). "The disease is dependent on IFNγ; IFNγ knockout (KO) mice exposed to S. rectivirgula develop alveolitis but not granulomas nor the subsequent fibrotic response." (PMID 21699708, 2011). "Previous studies indicated that IFNγ mediates expression and secretion of chemokines CXCL9, CXCL10, and CXCL11 in macrophages, resulting in the recruitment of CXCR3 bearing CD4+ Th cells and CD8+ Tc cells into the lung and granuloma formation in humans and mice." (PMID 39464896, 2024). "The notion that TB granulomas are host-protective is evinced indirectly from the observation that most individuals infected with Mtb – identified through positive tuberculin skin tests or IFNγ release assays – do not progress to active TB and commonly exhibit calcified granulomas." (PMID 39717773, 2024). "The immune response of TT patients is characterized by a Th1 cytokine response (interferon gamma [IFN-γ], interleukin (IL)-2, IL-15, and tumor necrosis factor [TNF]), vigorous T-cell responses to M. leprae antigens, and containment of the bacilli in well-formed granulomas." (PMID 28162092, 2017). "Although elevation of mRNA from the prototypical inflammatory cytokine, interferon gamma (IFN-γ), was below detectable limits in LCM samples of granulomatous foci, immunostaining confirmed the presence of numerous IFN-γ-expressing cells within 60-day MWCNT-induced granulomas." (PMID 23343389, 2013). "Finally, interleukin (IL)-2 and interferon gamma (IFN-γ) production by CD4 T cells was higher in patients with hepatomegaly, and chemokine receptor CCR5 known to be expressed on Th1 cells was shown to be higher on CD4 T cells in patients with granulomas, implying Th1 bias in these patients." (PMID 31803177, 2019). "The exposure of MAB induced granulomas to α-MSH decreased inflammatory cytokines (Il1β, Il-8, CCL3, CCL5, IFNγ, GM-CSF, IL-12) without altering the granuloma structure." (PMID 32751786, 2020).
Immunodeficiency (199 papers, 2005 to 2026). Failure of the immune system to protect the body adequately from infection, due to the absence or insufficiency of some component process or substance. "Most reported cases are in patients with some significant form of immunodeficiency, with a strong association between disseminated infection and anti-interferon-gamma antibodies." (PMID 41244294, 2025). "Both CXCL10 and 11 are pro-inflammatory cytokines positively regulated by IFNγ and their increased activity is associated with different immune disorders." (PMID 37470035, 2023). "The tumor immune dysfunction score, and exclusion score, dysfunction score, and Interferon Gamma score were significantly lower in the high-risk group than in the low-risk group, but the exclusion score was higher." (PMID 37543760, 2023). "Autoantibodies against interferon-gamma (AutoAbs-IFN-γ) can cause the immunodeficiency condition following various opportunistic infections." (PMID 35650243, 2022). "Whilst disseminated NTM infections are associated with severe immunodeficiency states such as HIV infection or defects in interferon gamma (IFNγ) and STAT3 pathways, the pathophysiology of localised pulmonary NTM infection is unclear." (PMID 28506264, 2017). "Autoantibodies against interferon-gamma (IFN-γ) can cause immunodeficiency and are associated with various opportunistic infections." (PMID 26727515, 2016). "Patients with immunodeficiency syndromes associated with anti-interferon-gamma (IFN-γ) autoantibodies are prone to a wide range of infections, particularly those caused by intracellular pathogens such as nontuberculous mycobacteria (NTM) or Talaromyces marneffei (T. marneffei)." (PMID 41013333, 2025). "In conclusion, we have summarized previous reports of anti-IFNγ antibody associated immunodeficiency and found that skin involvement, NTM infection, and recurrent infections might be associated with disease outcome." (PMID 37365453, 2023). "We recently reported the first case of germline loss of function mutations causing partial JAK1 deficiency in humans which resulted in immunodeficiency characterized by mycobacterial infection, suggesting a dominant effect on the IFNγ pathway, and high-grade bladder carcinoma." (PMID 31552026, 2019). "Studies of other human immunodeficiency states and of animal models suggest that deficiencies in IFNγ or IL-17 may predispose to S. aureus infections." (PMID 27093273, 2016). "Our data are consistent with the hypotheses that a shift from a parallel to an antiparallel dimer conformation of STAT1 is required for the termination of IFNγ-mediated gene expression and that a defect in this transition causes human immunodeficiency." (PMID 23922848, 2013). "Primary immune deficiencies, such as chronic granulomatous disease (CGD) or defects in the interferon-gamma and interleukin-12 pathways, are significant contributors to susceptibility to mycobacterial infections." (PMID 41300611, 2025). "Anti-IFNγ and anti-TNFα IgG were also increased, of particular interest because anti-cytokine autoantibodies can lead to immunodeficiency." (PMID 41445737, 2025). "Collectively, IFNG, IL2RG, FCGR3A, and ICAM1 associated with immune diseases were selected from the core genes through manual screening." (PMID 40844079, 2025). "In such scenarios of immune dysfunction, Interferon-gamma (IFNγ), a crucial immuno-regulatory cytokine, plays a pivotal role with dual biological functions." (PMID 40264756, 2025). "UC is classified as a TH2 type immune disease with an upregulation of interleukin (IL)-5 while CD is considered as TH1 type characterized by high levels of interferon gamma (IFN-γ), IL-12, and tumor necrosis factor alpha (TNF-α)." (PMID 40008255, 2025). "Our findings suggest that immune dysfunction in CPA involves DC and monocyte impairments, potentially contributing to IFNγ Deficiency through reduced IL-12 production and co-stimulatory capacity in cDC1s." (PMID 40503945, 2025).